MIR183 (microRNA 183)
Synonyms: hsa-mir-183; MIRN183; miR-183; miRNA183
Gene: MicroRNA gene on chromosome 7 (129,774,905 to 129,775,014, reverse strand). Ensembl gene ENSG00000207691.
Gene Ontology:
Molecular function: mRNA 3'-UTR binding; mRNA base-pairing post-transcriptional repressor activity
Biological process: miRNA-mediated post-transcriptional gene silencing
Cellular component: RISC complex
Homologues: Orthologues: chimpanzee ptr-mir-183 (100% identical), macaque mml-mir-183 (97% identical), dog MIR183 (91% identical), zebrafish dre-mir-183 (78% identical), tropical clawed frog xtr-mir-183 (75% identical), guinea pig MIR183 (64% identical), mouse Mir183 (64% identical), pig ssc-mir-183 (63% identical), rabbit MIR183 (63% identical).
Diseases named in the same sentence as MIR183 in open-access papers:
MIR183 is named in the same sentence as 11 diseases in open-access papers, as found by Europe PMC text mining. Sharing a sentence is not in itself a finding about the gene and the disease. The quoted sentences say what the papers report.
glioma (2 papers, 2013 to 2021). A benign or malignant brain and spinal cord tumor that arises from glial cells (astrocytes, oligodendrocytes, ependymal cells). "MIR135B, MIR182 and MIR183 are overexpressed in a wide range of other cancer types such as bladder, colon, prostate cancer and glioma." (PMID 24053169, 2013). "Although many of the up-regulated miRNAs that we found are not known to participate in CNS tumors, MIR183 has been previously reported to be up-regulated in glioblastoma and glioma." (PMID 34204289, 2021).
deafness (1 paper, 2020). An inherited or acquired condition characterized by the complete loss of the ability to hear from one or both ears. "Of the genes misregulated in Mir183/96dko homozygotes, five are known deafness genes; Myo3a, Slc26a5 and Tmc1 underlie deafness in mice and humans, while mutations in Sema3e cause deafness in people, and mice lacking Ocm exhibit progressive hearing loss." (PMID 33318051, 2020).
hearing loss (1 paper, 2018). "Germline mutations in Mir96, one of three co-expressed polycistronic miRNA genes (Mir96, Mir182, Mir183), cause hereditary hearing loss in humans and mice." (PMID 29476110, 2018).
mammary tumor (1 paper, 2022). "Similarly, several exosome-derived miRNA orthologs previously reported for increased expression in both canine and human mammary tumor cell lines, including MIR21, MIR106B, MIR181A1, MIR183, MIR200B, and MIRLET7G, were presented." (PMID 35765483, 2022).
tumor (2 papers, 2023 to 2024). "We identified MIR182, MIR183, MIR371, MIR373, MIR512-1, MIR512-2, MIR515-1, and MIR520e exhibiting high expression and MIR216b, MIR887, MIR9-2, and MIR9-3 exhibiting low expression in NANOG H/L tumours." (PMID 38693576, 2024). "However, the correlation between Mir183 and Txnip expression described for neuropathic pain could not be found in the present study in tumor cells." (PMID 38069241, 2023).
MIR183 also shares sentences with these, for which no sentence is quoted: cancer (1 paper); CNS tumors (1); glioblastoma (1); pancreatic adenocarcinoma (1); periodontitis (1); prostate carcinoma (1).